UBE2L5 (ubiquitin conjugating enzyme E2 L5)
Description:
Catalyzes the covalent attachment of ubiquitin to other proteins.
Synonyms: UBCH7N2; UBE2L5P
Gene: Protein-coding gene on chromosome 13 (30,422,488 to 30,429,758, forward strand). Ensembl gene ENSG00000236444.
Subcellular location (Human Protein Atlas): Cytosol; Nucleoplasm; Primary cilium transition zone
Gene Ontology:
Molecular function: ubiquitin conjugating enzyme activity; ubiquitin-like protein transferase activity
Biological process: protein K11-linked ubiquitination; ubiquitin-dependent protein catabolic process; protein modification by small protein conjugation; protein ubiquitination
Genetic constraint (gnomAD): Loss-of-function variants: 3 observed, 9.18 expected, observed/expected ratio (o/e) 0.33, 90% interval 0.15 to 0.85. That is too few expected variants to judge how well the gene tolerates losing a copy. Missense variants: 124 observed, 184.8 expected, observed/expected ratio (o/e) 0.67, 90% interval 0.58 to 0.78. Synonymous variants: 57 observed, 66.67 expected, observed/expected ratio (o/e) 0.86, 90% interval 0.69 to 1.07.
Homologues: Orthologues: chimpanzee UBE2L5 (100% identical), macaque UBE2L5 (99% identical), guinea pig UBE2L3 (97% identical), mouse Ube2l3 (97% identical), rat Ube2l3 (97% identical), zebrafish ube2l3a (92% identical), tropical clawed frog ube2l3 (90% identical), zebrafish ube2l3b (88% identical). Paralogues in human: UBE2L3 (97% identical), UBE2L6 (55% identical), UBE2D4 (40% identical), UBE2D2 (38% identical), UBE2D1 (37% identical), UBE2D3 (37% identical), UBE2E2 (34% identical), UBE2E3 (34% identical), UBE2E1 (34% identical), UBE2Q2 (23% identical), UBE2Q1 (22% identical), UBE2QL1 (19% identical).